PIAS3 (protein inhibitor of activated STAT 3)
Diseases named in the same sentence as PIAS3 in open-access papers (continued):
Sharing a sentence is not in itself a finding about the gene and the disease.
gastric cancer (12 papers, 2012 to 2025). A primary or metastatic malignant neoplasm involving the stomach. "The miR-BART5-5p molecule directly targets PIAS3 and enhances the expression of PD-L1 through the regulation of the miR-BART5/PIAS3/pSTAT3/PD-L1 axis in EBV-associated gastric carcinomas." (PMID 38462628, 2024). "Interaction between miRNA-18a and PIAS3 has been implicated in the development of gastric cancer through the overactivation of STAT3 when PIAS3 is silenced." (PMID 31842362, 2019). "In gastric cancer, EBV-encoded miRNA-BART5-5p activates the PIAS3/pSTAT3/PD-L1 axis to significantly enhance PD-L1 expression, leading to an immunosuppressive tumor microenvironment." (PMID 40296912, 2025). "The qRT-PCR analysis revealed that PIAS3 was higher than in the human gastric cancer cells than in the BSA control group after treatment with 150 μM of PA for 12–24 h or treatment with 75–150 μM of PA for 24 h." (PMID 36672337, 2023). "The Kaplan–Meier survival analyses indicated that low PIAS3 expression was common in patients with gastric cancer, especially those with stage III gastric cancer." (PMID 36672337, 2023). "In fact, several miRs, including miR‐18a, have been reported to regulate PIAS3 expression in other diseases, including gastric cancer, multiple myeloma, and chronic lymphocytic leukemia." (PMID 30259640, 2018). "Consistently, lower PIAS3 expression has also been observed in gastric cancer and squamous cell carcinoma of the lung." (PMID 26768588, 2016). "miR-BART5-5p overexpression in EBV negative gastric cancer cells caused a reduction of PIAS3 and then STAT3 stimulation followed by PD-L1 upregulation." (PMID 40855561, 2025). "In addition, high PIAS3 expression promoted the invasion and migration of gastric cancer and was strongly negatively correlated with the survival of patients." (PMID 38528630, 2024). "PIAS3 dysregulation is crucial in inflammatory diseases and cancers, including gastric cancer." (PMID 36672337, 2023). "Others have found that hsa-miR-18a-5p targets PIAS3 directly and in this way causes an increase in STAT3 transcriptional activity in gastric cancer cell lines fitting with the hypothesis for hsa-miR-637." (PMID 31063487, 2019). "This hypothesis is further supported by the loss of expression of PIAS3, the target of TRIM8, in many tumors including human gastric carcinoma and glioblastoma multiforme tumors." (PMID 23152791, 2012). "However, the mechanisms by which the p-STAT3/PIAS3 pathway regulates the occurrence and development of gastric cancer remain unclear." (PMID 36672337, 2023). "Recent work reported that overexpression of miR-18a could promote cell proliferation in gastric cancer by regulating PIAS3 expression and consequentially increase STAT3 activity, leading to enhanced activation of genes downstream of STAT3 modulated by CASC2-targeting miRNAs." (PMID 27198161, 2016). "Our findings demonstrate that PA exerts anti-gastric cancer effects by regulating key molecules (p-STAT3 and its inhibitor PIAS3) in the STAT3-PIAS3 signaling pathway." (PMID 36672337, 2023). "The qRT-PCR analyses indicated that PIAS3 was expressed at lower levels in the human gastric cancer cell lines (MGC-803, SGC-7901, and AGS) and the clinical gastric cancer tissues compared to that in the GES-1 cells and the paracancerous tissues." (PMID 36672337, 2023). "Our findings demonstrated that PA exerted anti-gastric cancer effects by regulating key molecules in the signal transduction and activation of a transcription 3 (STAT3) protein inhibitor of the activated STAT 3 (PIAS3) signaling pathway." (PMID 36672337, 2023). "PIAS3 levels were higher in the MGC-803 gastric cancer cells exposed to 150 μM of PA for 12 h than in the cells exposed to BSA, indicating that PIAS3 plays a crucial role in PA-induced inhibition of proliferation and metastasis in human gastric cancer cells." (PMID 36672337, 2023).
gastric cancer (continued). "Our results indicated that PIAS3 mRNA levels increased gradually as the PA treatment duration or the PA concentration increased, consistent with our findings relating to p-STAT3 protein expression in human gastric cancer and normal cells." (PMID 36672337, 2023).
lung carcinoma (9 papers, 2014 to 2024). "In several cancers a decrease or loss of PIAS3 expression was demonstrated, indicating it as a protein with putative tumor suppressor function, but a paucity of studies were focused on lung cancer." (PMID 25137041, 2014). "PIAS3 in turn suppresses the proliferation of lung cancer cells through SUMO-independent inhibition of STAT3 and PI3K/AKT signaling, as well as via the promotion of apoptosis." (PMID 34503213, 2021). "PIAS3 has been known to control STAT3 transcriptional activity in lung cancer cells through affecting its DNA transcriptional properties and STAT3 phosphorylation." (PMID 25788267, 2015). "This was validated by our finding of low to negligible PIAS3 staining by immunohistochemistry in almost 50% of SCC tumor cores on a lung cancer TMA." (PMID 25573684, 2015). "In addition, miR‐31 has high homology binding to the PIAS3 3′UTR and has been reported as an onco‐miR in lung cancer and is associated with a poor prognosis in MM, although this is controversial." (PMID 30259640, 2018). "Thus, amplified PIAS1 and SENP2 are potential therapeutic targets in lung cancer, whereas the expression level of PIAS3 may predict sensitivity towards select treatments." (PMID 34503213, 2021). "Although various oncogenic targets have been described to account for the potent anticancer activities of BSN, our study is the first one to explore the effects of BSN both on STAT3 signaling pathway and on the negative regulators of STAT3 signaling (PIAS-3 and SOCS-3) in human lung carcinoma." (PMID 25788267, 2015). "Additionally, the targeted therapy toward STAT activity might be based on the data regarding PIAS3 and/or COX-2 expression in lung cancer cells." (PMID 25137041, 2014).
prostate carcinoma (7 papers, 2015 to 2024). A carcinoma that arises from epithelial cells of the prostate gland. "PIAS3 is expressed in prostate cancer cells, and its expression is induced in response to androgens." (PMID 31835700, 2019). "PIAS3 normally inhibits the transactivation function of Stat5, an effect which is circumvented by the truncation of the amino terminal domain in prostate cancer cells." (PMID 25809097, 2015). "PIAS3 also interacts with AR as co-regulator in prostate cancer." (PMID 38590645, 2024). "Professor Alanne identified PIAS3 as a potential biomarker for Gleason score 4 + 3 = 7 for prostate cancer and UBE2V2 as a potential biomarker for Gleason score 6, while Professor ElKarami created a model for predicting upgrading on magnetic resonance imaging targeted biopsy by machine learning." (PMID 35978830, 2022). "Although PIAS has been shown to enhance the transcriptional activity of androgen receptors (AR) in prostate cancer cells, other studies have revealed that ectopic overexpression of PIAS3 suppresses AR-mediated gene activation induced by dihydrotestosterone (DHT)." (PMID 31835700, 2019). "Thus, the proteolytic cleavage of the N-terminus of Stat5a/b may be a mechanism by which Stat5 evades the transcriptional repression by PIAS3 in prostate cancer cells." (PMID 31835700, 2019).
colorectal cancer (6 papers, 2014 to 2024). A primary or metastatic malignant neoplasm that affects the colon or rectum. "PIAS3 level is negatively associated with aberrant expression of STAT3 and its downstream targets such as survivin, Bcl-xL, and c-Myc in colorectal cancer." (PMID 38590645, 2024). "miR-199a-5p and microRNA-543 participate in cancer progression and proliferation via targeting the PIAS3 in cervical cancer and colorectal cancer." (PMID 38590645, 2024). "For instance, CASC2 is able to repress the expression of miR-18a-5p, thereby inducing PIAS3 (Protein Inhibitor of Activated STAT 3) expression in colorectal cancer cells." (PMID 32549759, 2020). "Recently, it was demonstrated that CASC2 in colorectal cancer is functioning as ceRNA for miR-18a, thereby modulating the expression of target gene PIAS3, and subsequently inhibiting CRC cell proliferation and tumor growth." (PMID 33120918, 2020).
colitis (5 papers, 2016 to 2024). Inflammation of the colon. "Contrary, the studied extract at a higher dose (100 mg/kg) significantly elevated PIAS3 mRNA expression nearly 2.5-fold in comparison to the colitis group (p < 0.05)." (PMID 37049797, 2023). "The difference in total gut length was minimal between the two groups; however, both ileitis and colitis scores were significantly lower in PIAS3-treated mice." (PMID 30630513, 2019). "Interestingly, nuclear actin polymerization is highly related with expression of PIAS3, which modulates signal transducer and activator of transcription 3 and NF-κB activity in colitis." (PMID 39183944, 2024). "Thus, nuclear actin polymerization was confirmed to play roles in moderating colitis-related gene PIAS3 expression." (PMID 39183944, 2024).
glioma (5 papers, 2010 to 2023). A benign or malignant brain and spinal cord tumor that arises from glial cells (astrocytes, oligodendrocytes, ependymal cells). "Nevertheless, our data are an important step for understanding PIAS3 loss in gliomas and identifying new targeted therapeutic strategies." (PMID 29950561, 2018). "Survival analysis indicated that low PIAS3 protein level in gliomas was associated unfavorable survival outcome." (PMID 29950561, 2018). "The present study reveals a mechanism underlying PIAS3 loss in gliomas and explains the previous finding that PIAS3 loss in gliomas at protein level, and not at mRNA level." (PMID 29950561, 2018). "In contrast, overexpression of PIAS3 in the U251-MG human glioma cell line inhibited the expression of the OSM-enhanced STAT3 target genes (e.g., Survivin, Bclxl, and SOCS3), which resulted in reduction of cell proliferation by 80%." (PMID 36923251, 2023). "Mechanistically, SMAD6 promotes PIAS3 degradation, promoting glioma cell growth and stem cell properties." (PMID 31557897, 2019). "Immunoprecipitation (IP) experiments determined that the endogenous interaction between Smad6 and PIAS3 exists in glioma cells." (PMID 29950561, 2018). "The patient-derived glioma cells (T06) expressing high Smad6 and low PIAS3 were implanted into mouse brains." (PMID 29950561, 2018). "First, we measured PIAS3 expression in patient-derived glioma cells and revealed that PIAS3 expression was negatively correlated to the xenografts tumorigenic potential." (PMID 29950561, 2018). "In conclusion, our results highlight key roles of nuclear-Smad6 as a new regulator of STAT3 through PIAS3 interaction in gliomas." (PMID 29950561, 2018). "As PIAS3 acts as a tumor repressor in GBM, we further determined the effects of MH2-mediated Smad6–PIAS3 interaction on glioma biological phenotypes." (PMID 29950561, 2018). "It showed that PIAS3 expression inversely correlated with nuclear-Smad6 in glioma tissues (Spearman’s r = − 0.3323, P < 0.0001)." (PMID 29950561, 2018). "Collectively, we conclude that nuclear-Smad6 enhances glioma development by inducing PIAS3 degradation and subsequent STAT3 activity upregulation." (PMID 29950561, 2018). "Here we provide evidence to connect elevated Smad6 and low PIAS3 to constitutive STAT3 activity in gliomas." (PMID 29950561, 2018). "Surprisingly, the present study also showed a positive correlation between SMAD6 and PIAS3 at mRNA level in gliomas." (PMID 29950561, 2018). "To uncover the clinical implication of PIAS3, we detected PIAS3 expression in human glioma tissues using IHC." (PMID 29950561, 2018). "In view of different subcellular expression of PIAS3 between neuron and astrocyte/glioma cell, we determined the PIAS3 expression in nuclei in glioma tissues." (PMID 29950561, 2018). "PIAS3 was determined to be expressed in nuclei of primary glioma cells." (PMID 29950561, 2018). "It indicated that PIAS3 is expressed in nuclei of normal astrocytes in vitro and in vivo, cytoplasm of neurons in vivo, and nuclei of glioma cells in GBM tissues." (PMID 29950561, 2018). "In the STAT3 signalling pathway of glioma, miRNAs can directly target STAT3 mRNA, genes closely related to STAT3 activation (PIAS3, SOCS3), and upstream genes of STAT3." (PMID 34425834, 2021). "In this study, we report that Smad6 is overexpressed in nuclei of glioma cells, which correlates with poor patient survival and regulates STAT3 activity via negatively regulating the Protein Inhibitors of Activated STAT3 (PIAS3)." (PMID 29950561, 2018). "Here, the authors show that Smad6 expression correlates with poor survival and is overexpressed in glioma cells, and regulates STAT3 activity via negatively regulating PIAS3." (PMID 29950561, 2018). "The complicated mechanisms of PIAS3 in tumorigenesis indicate that besides STAT3, other potential downstream pathways mediating the cancer-promotion of Smad6–PIAS3 axis in gliomas still need to be studied." (PMID 29950561, 2018).
glioma (continued). "Although PIAS3 is closely associated with STAT3 and Smad6 interacts to PIAS3, we did not observe direct interaction between Smad6 and STAT3 in glioma cells." (PMID 29950561, 2018). "It discovered that PIAS3 protein levels were substantially lower in glioma tissues from stage II/III to stage IV tissues than it in normal brains." (PMID 29950561, 2018). "Consequently, Smad6 reduces PIAS3-mediated STAT3 inhibition and promotes glioma cell growth and stem-like cell initiation." (PMID 29950561, 2018). "Furthermore, inhibition of PIAS3 by RNA interference in the U87-MG human glioma cell line promoted cell proliferation despite less or no change in STAT3 phosphorylation." (PMID 36923251, 2023).
atherosclerosis (4 papers, 2016 to 2023). A disease characterized by the build-up of fatty material and calcium deposition in the arterial wall resulting in partial or complete occlusion of the arterial lumen. "Atherosclerosis progression is associated with PIAS3 downregulation, suggesting that PIAS3 plays a crucial role in attenuating atherosclerosis development." (PMID 27845432, 2016). "We previously found that PIAS3 was negatively associated with the JAK2/STAT3 activation and inflammatory responses in macrophages during atherosclerosis." (PMID 37008329, 2023). "To confirm the association between PIAS3 and atherosclerosis and assess JAK/STAT3 signalling activation and inflammation during atherosclerosis, we analysed PIAS3, STAT3-Y705, STAT3 and IκBα protein expression in aortas using Western blotting." (PMID 27845432, 2016). "We found that PIAS3 is inversely correlated with atherosclerosis progression and is a repressor for atherosclerosis-related cellular responses." (PMID 27845432, 2016). "Then, we used the atherogenic stimuli IL-6 and ox-LDL to stimulate cultured cells to assess PIAS3 expression in the setting of atherosclerosis-induced inflammation." (PMID 27845432, 2016). "Here, we observed that PIAS3 levels are reduced in atherosclerotic lesions and that PIAS3 expression decreases in conjunction with increases in interleukin-6 expression and atherosclerosis severity." (PMID 27845432, 2016). "In conclusion, we determined that PIAS3 expression is inversely correlated with atherosclerosis development." (PMID 27845432, 2016). "To assess PIAS3 expression and its correlation with atherosclerosis development, we fed wild-type (WT) mice and ApoE−/− mice chow or western diets for 20 weeks." (PMID 27845432, 2016). "Whereas, the inhibitor of the JAK/STAT3 pathway, such as protein inhibitor of activated STAT-3 (PIAS3), may be a critical repressor of atherosclerosis." (PMID 32283795, 2020). "Hence, we performed a series of experiments using cultured cells to determine the effects of PIAS3 on atherosclerosis and found that PIAS3 overexpression suppressed ox-LDL-induced inflammation, lipid accumulation and VSMC proliferation." (PMID 27845432, 2016). "Our data suggest that PIAS3 is a critical repressor of atherosclerosis progression." (PMID 27845432, 2016). "Thus, the objective of this study was to analyse PIAS3 expression and its roles in cellular responses during atherosclerosis." (PMID 27845432, 2016). "PIAS3 upregulation should be explored as a potential strategy for treating atherosclerosis." (PMID 27845432, 2016). "In addition, we investigated the effects of PIAS3 on atherosclerosis-related cellular responses, including inflammatory cytokine expression, foam cell formation and cell proliferation, and also examined the potential mechanisms underlying these processes." (PMID 27845432, 2016). "Interestingly, PIAS3 expression levels decreased significantly in conjunction with atherosclerotic deterioration, suggesting that PIAS3 levels in aortas are inversely correlated with atherosclerosis development." (PMID 27845432, 2016). "Our results indicate that PIAS3 suppressed ox-LDL-induced inflammation, lipid accumulation in macrophages and VSMC proliferation, which are that main cellular responses that occur during atherosclerosis." (PMID 27845432, 2016). "We found that PIAS3, a key negative regulator of JAK/STAT3 signalling, was downregulated in atherosclerotic aortas in mice and that its expression may be inversely correlated with atherosclerosis progression." (PMID 27845432, 2016). "However, the involvement of PIAS3 in atherosclerosis development has not yet been defined." (PMID 27845432, 2016). "Interestingly, we found that PIAS3 expression, unlike SOCS1 expression, exhibits significant declines, even during the early stages of atherosclerosis." (PMID 27845432, 2016).